TSC2 (TSC complex subunit 2)
Diseases named in the same sentence as TSC2 in open-access papers (continued):
Sharing a sentence is not in itself a finding about the gene and the disease.
tuberous sclerosis (continued). "Molecular diagnosis of tuberous sclerosis is established through the identification of a pathogenic variant of TSC1 or TSC2, regardless of the clinical findings." (PMID 39144255, 2024). "Additionally, there is a suggestion that variants in the tuberous sclerosis genes predispose to ganglioglioma, with several polymorphisms and alterations in TSC1 and TSC2 having been identified in these tumours." (PMID 39294363, 2024). "A case series studying patients with FCCH in tuberous sclerosis patients identified heterozygous pathogenic variants in the TSC2 gene in tumor tissue samples, without evidence of a TSC2 second hit, suggesting a potential genotype-phenotype correlation." (PMID 38989358, 2024). "TSC2 in the tuberous sclerosis complex tightly regulates mTORC1 activation." (PMID 37788104, 2023). "Tuberous sclerosis complex is considered to be caused by pathogenic germline mutations (e.g., single nucleotide variations, deletions, insertions, and copy number variations) in either the TSC1 or TSC2 gene." (PMID 36732866, 2023). "Tuberous sclerosis (Bourneville disease) results from a mutation in the TSC1 and TSC2 genes." (PMID 38021712, 2023). "Several mutations in TSC2 and TSC1 cause tuberous sclerosis complex." (PMID 36611753, 2022). "Tuberous sclerosis is usually due to TSC1 and TSC2 mutations." (PMID 35449076, 2022). "TSC2, a tumour suppressor complex, is part of the tuberous sclerosis complex." (PMID 34085405, 2021). "Additionally, in an in vivo study on a mouse model of tuberous sclerosis complex (TSC), the mutation in either TSC1 or TSC2 can disturb the function of NMDA receptors in the EI, which in turn can cause a shift from normal activity to ictal activity." (PMID 35002598, 2021). "Tuberous sclerosis complex (TSC), formerly known as Bourneville Disease, is an autosomal dominant neurocutaneous disorder due to mutations in TSC1 or TSC2, two tumor suppressor genes belonging to the GATOR1 complex that negatively regulates mTOR-PIK3CA pathway." (PMID 35096710, 2021). "In 25 patients (13.6%), variations were identified in TSC1, whereas in 85 patients (46.2%), variations were observed in TSC2 (TSC1:TSC2 ratio 1:3.4), and five patients (2.7%) suffered from a polycystic kidney disease with tuberous sclerosis (PKDTS), which is a contiguous gene deletion syndrome." (PMID 34154622, 2021). "Specifically, in the radial glial cells of knock out mouse models of tuberous sclerosis (TSC2-RG mice) metabolic shifts towards anabolic pathways with increased glutaminolysis and pentose phosphate pathway activity were both noted in tuberous sclerosis mice models." (PMID 32341806, 2020). "According to the NIH, tuberous sclerosis is an autosomal dominant genetic disorder that ultimately leads to benign tumor growth in multiple organs of the body and it is cardinally seen with mutations in either TSC1 or TSC2." (PMID 32341806, 2020). "Additionally, we identified a pathogenic variant of TSC2 in AU039303, who was rediagnosed with tuberous sclerosis and epilepsy." (PMID 30763456, 2019). "Indications of an increased risk were found for de novo tuberous sclerosis and Sturge–Weber syndrome, which suggest that maternal smoking during pregnancy might affect mutagenesis in TSC1, TSC2, and GNAQ." (PMID 31564984, 2019). "Transgenic mouse models of tuberous sclerosis such as Tsc2+/− and Tsc1+/− exhibit increased activity in the mTOR pathway, which is accompanied by deficits in long-term potentiation and spatial learning, which can be reversed by chronic treatment with a rapamycin, a mTOR pathway inhibitor." (PMID 30083288, 2018).
tuberous sclerosis (continued). "The mechanism by which TSC2 inactivation or deficiency contributes to the pathology of tuberous sclerosis complex (TSC) is not fully clear." (PMID 29491408, 2018). "Tuberous sclerosis complex is closely related to the TSC1/TSC2 genes." (PMID 30185235, 2018). "The TSC2 c.3599G>C (p.R1200P) variant has been included in the tuberous sclerosis database (LOVD), but without any information on the patients’ clinical manifestations." (PMID 29308833, 2017). "Mutations in TSC1 or TSC2 cause tuberous sclerosis, which results in non-malignant tumors in the brain, autistic behavior, intellectual disability, and seizures." (PMID 27008623, 2016). "As a result, enhanced degradation of TSC2 by Phr1 might directly impact a subset of patients with tuberous sclerosis." (PMID 27008623, 2016). "Since discovering the TSC2 gene in 1993 (European Chromosome 16 Tuberous Sclerosis Consortium, 1993), investigative research efforts have quickly produced a plethora of experimental data leading to the development of the first generation of therapeutics for TSC and LAM." (PMID 25505789, 2014). "Dysregulated TSC/mTOR signaling may play a pathogenetic role in forms of syndromic autism, such as autism associated with tuberous sclerosis, a genetic disorder caused by heterozygous TSC1 or TSC2 mutations." (PMID 25114803, 2014). "We sought to extend the behavioral analysis to other characteristic behaviors found in tuberous sclerosis, namely autistic perseverative behavior, and to determine if these behaviors in TSC2+/− mice could be due to heightened mGluR5 signaling." (PMID 23966835, 2013). "Interestingly, animal models of tuberous sclerosis (Tsc2+/− mice) and fragile X syndrome (Fmr1−/y mice) display abnormal protein synthesis in opposite directions." (PMID 23935565, 2013). "Similarly, analysis of Nf1−/− and Tsc2+/− mice has suggested treatments to correct behavioral impairment in neurofibromatosis and tuberous sclerosis complex (TSC)." (PMID 22558107, 2012). "Tuberous sclerosis is an autosomal dominant disorder characterized by multiple benign hamartomas and neoplasms caused by the disruption of a pair of tumor suppressor genes, TSC1 and TSC2, which encode for hamartin and tuberin, respectively." (PMID 22018000, 2011). "Recent data from Ellisen and colleagues suggest that a primary Ddit4 mechanism of action is to competitively bind inhibitory 14-3-3 proteins that otherwise bind to the Tsc2 protein, part of the tuberous sclerosis complex that inhibits Akt/Frap1 signaling when Tsc2 is unbound." (PMID 19370158, 2009). "Although it frequently appears in tuberous sclerosis—a condition more often associated with a mutation in the TSC2 tumor suppressor gene rather than TSC1, which aberrantly activates the mTOR pathway—LAM is commonly diagnosed in its sporadic form (S-LAM), primarily affecting the lungs." (PMID 39858105, 2025). "Tuberous Sclerosis (TS) is a rare multisystem genetic disease characterized by autosomal dominant inheritance caused by mutations in the TSC1 (located on chromosome band 9q34) and TSC2 (located on chromosome band 16p13.3) genes, which leads to changes in cell differentiation and proliferation." (PMID 38311784, 2024). "Pulmonary LAM has been identified as being associated with tuberous sclerosis complex (TSC) in its pulmonary manifestation (TSC-LAM), a multisystem genetic disorder resulting from mutations in either the TSC1 or TSC2 genes." (PMID 38596252, 2024). "For example, a nonsense variant in TSC2 (NM_000548.5:c.4081C > T) was reported in ClinVar (SCV000819981.3) as a variant of uncertain significance after it was identified in an individual without features of tuberous sclerosis complex." (PMID 38012313, 2024). "Observed mainly in women of childbearing age, LAM can be associated with tuberous sclerosis complex (TSC-LAM) involving germline mutations of the TSC1 and TSC2 genes, or in sporadic form involving somatic mutations of the TSC2 gene." (PMID 39845810, 2024).
tuberous sclerosis (continued). "Tuberous sclerosis (TSC) is an autosomal dominant neurocutaneous syndrome resulting from mutations in the tumor suppressor genes TSC1 and TSC2." (PMID 39432612, 2024). "Dysregulated mTORC1 signalling is also well documented in the inherited condition Tuberous Sclerosis Complex (TSC), due to loss of function mutations in the upstream mTORC1 regulators, TSC1 and TSC2." (PMID 37337371, 2023). "Since in Tuberous Sclerosis there is hyperactivation of mTORC1 and subsequently hyperphosphorylation of its downstream effectors, 4E-BPs and S6Ks, we reasoned that Nlgn1 mRNA translation might be increased in Tsc2+/− hippocampi." (PMID 37293130, 2023). "Ultimately, future studies will reveal whether Tfeb and/or Tfe3 deletion is sufficient to reduce renal tumorigenesis in mice with spontaneous or inducible loss of Tsc2, and establish whether MiT/TFE targeting could be therapeutically useful in the setting of human tuberous sclerosis." (PMID 36357396, 2022). "Tuberous sclerosis (TSC) and its domains (Tsc1 and Tsc2) are responsible for autosomal-dominating disorders, including epilepsy, skin, retina, heart, kidney, and the central nervous system." (PMID 36362447, 2022). "Therefore, we believe that although TSC2 gene variation was detected in this case, it did not meet the diagnostic criteria of tuberous sclerosis." (PMID 36510186, 2022). "An increasing number of patients with TSC have undergone TSC1/TSC2 genetic testing since the presentation of the genetic diagnosis of TSC at the 2012 International Tuberous Sclerosis Complex Consensus Conference." (PMID 35246210, 2022). "The aim of this study was to assess the potential implication of microRNA on tuberous sclerosis (TSC) pathogenesis by performing microRNA profiling on cell lines silencing TSC1 or TSC2 genes using qPCR panels, before and after incubation with rapamycin." (PMID 36430972, 2022). "Tuberous sclerosis complex (TSC) is a genetic disease characterized by benign tumors, epilepsy, ASD, and loss of function of Tsc2 due to missense mutations in TSC patients." (PMID 34497307, 2021). "A variety of epithelial renal neoplasms have been identified both in patients with tuberous sclerosis complex (TSC) and in the nonsyndromic setting associated with somatic mutations in the TSC1 and TSC2 genes." (PMID 34680979, 2021). "Tuberous sclerosis complex (TSC) is a rare autosomal dominant neurocutaneous syndrome (incidence of approximately 1/6000 live births) caused by mutations in the genes TSC1 and TSC2, which encode hamartin and tuberlin." (PMID 33271987, 2020). "In approximately 85% of cases, TSC has been associated with genetic variations in two specific genes: tuberous sclerosis complex 1 (TSC1) and 2 (TSC2)." (PMID 32873234, 2020). "The TSC1 and TSC2 genes are connected to multiple syndromes from Tuberous Sclerosis Complex (TSC) to autism spectrum disorder (ASD), with uncertainty if genetic variants cause all or subsets of phenotypes based on the location and type of change." (PMID 33071758, 2020). "Another condition, tuberous sclerosis (TSC), involves mutation of either TSC1 and TSC2 genes that codes for proteins hamartin and tuberin, which act as tumor suppressors that regulate cell growth and the mTORC1 complex." (PMID 33519379, 2020). "The TSC2 variant was not returnable as the participant had elected to receive results related only to hypercholesterolemia or colon polyps; however the participant had been diagnosed with tuberous sclerosis while living." (PMID 32377377, 2020). "The intrinsic GTPase of Rheb is activated by Tsc1 and Tsc2, which are the gene products responsible for tuberous sclerosis complex (TSC)." (PMID 31454940, 2019). "And they are often associated with tuberous sclerosis complex (TSC), which is an autosomal dominant genetic disease because of losses of TSC1 (9q34) or TSC2 (16p13.3) genes." (PMID 30111336, 2018).
tuberous sclerosis (continued). "The TSC1 (Tuberous Sclerosis 1) and TSC2 (Tuberous Sclerosis 2) genes have an important role in the aetiology of Tuberous Sclerosis Complex (TSC)." (PMID 27499730, 2016). "Tuberous sclerosis (TSC) is associated with germline mutations in the TSC1/Harmatin (MIM605284) and TSC2/Tuburin (MIM191092) genes." (PMID 23369289, 2013). "Neurofibromin 1 (NF1), tuberous sclerosis complex (TSC1/TSC2), and phosphatase and tensin homolog (PTEN) are genes associated with neurological diseases with common autistic symptoms including neurofibromatosis, tuberous sclerosis, and Cowden/Lhermitte-Duclos syndrome." (PMID 23935565, 2013). "Four individuals were diagnosed with tuberous sclerosis: patient 15 with a SNV in the TSC1 gene, patient 16 with a SNV in the TSC2 gene, and patients 17 and 18 with deletions that also encompassed the TSC2 gene." (PMID 40428344, 2025). "LAM may present sporadically (S-LAM) or in association with tuberous sclerosis complex (TSC-LAM), which is caused by mutations in the TSC1 and TSC2 tumor suppressor genes." (PMID 40641534, 2025). "For example, larger gene deletion syndrome such as ‘TSC2 and PKD1 deletion’ has been described as a contiguous gene deletion syndrome, ‘Polycystic kidney disease, infantile severe, with tuberous sclerosis (OMIM: 600273)’, as PKD1 is in close proximity to TSC2." (PMID 38265426, 2024). "More exciting, however, was a case (case 11) clinically diagnosed with Tuberous Sclerosis, and for which previous extensive testing of the TSC1 and TSC2 genes was unremarkable." (PMID 38540401, 2024). "Tuberous Sclerosis (TSC), an autosomal-dominant multiorgan disorder caused by TSC1 gene (hamartin; chromosome 9q34) or TSC2 gene (tuberin; chromosome 16p13.3) mutations, is characterized by the development of hamartomatous lesions in various organs, including the brain." (PMID 38393374, 2024). "The tuberous sclerosis complex, comprised of TSC1, TSC2 and TBC1D7 components, negatively regulates mTORC1 through Rheb GAP activity." (PMID 38746323, 2024). "Tuberous sclerosis TSC is an autosomal-dominant multi-system disorder that results from pathogenic variants in the tumor suppressor genes, TSC1 and TSC2, leading to aberrant activation of the mTOR pathway and often presenting with renal cysts associated with cilia disruption." (PMID 38292052, 2023). "Tuberous sclerosis (TSC) is a hereditary systemic disease characterized by systemic hamartoma, with TSC1 and TSC2 identified as the genes responsible for this condition." (PMID 36362756, 2022). "As TSC2, the gene responsible for tuberous sclerosis, is adjacent to PKD1, the gene responsible for ADPKD, TSC2/PKD1 contiguous gene deletion syndrome is found in 2–5% of all tuberous sclerosis patients with renal cysts." (PMID 36362756, 2022). "Tuberous sclerosis, a disease in which mTORC1 is over-activated by TSC1 or TSC2 deletion, which leads to the formation of a wide range of benign tumors, is also direct evidence that mTORC1 plays a key role in tumorigenesis." (PMID 35558559, 2022). "Tuberous sclerosis (TSC) is a systemic, autosomal dominant genetic disorder caused by mutations of TSC1 or TSC2 genes that result in a constitutive activation of mTORC1 disturbing subsequently cellular differentiation, proliferation, and migration early in development." (PMID 32973442, 2020). "Tuberous sclerosis, which is a monogenic disease and causing cystic lesions and angiomyolipomas in kidneys as well as other multisystemic abnormalities, mutations in TSC1 or TSC2 leads hyperactivation of mTOR and mTOR inhibitors might be the first effective treatment for these patients." (PMID 31658846, 2019). "Just as regional TSC1 and TSC2 gene expression patterns contribute to the development of tumors and hamartomas elsewhere in the body, we hypothesized that regional TSC1/TSC2 expression in the brain may influence neuroanatomic and cognitive changes associated with tuberous sclerosis." (PMID 30190613, 2018).
tuberous sclerosis (continued). "Inhibition of ERK restores both GSK3β activity and levels of protein synthesis in Tsc2−/− cells, thus identifying ERK as a candidate therapeutic target for the treatment of tuberous sclerosis." (PMID 28646232, 2017). "Here, we report that patient-derived fibroblasts from three monogenic models of ASD—fragile X and tuberous sclerosis TSC1 and TSC2 syndromes—display depressed Ca2+ release through inositol trisphosphate receptors (IP3Rs)." (PMID 26393489, 2015). "Since the finding that the tuberous sclerosis genes TSC1 and TSC2 are suppressors of the mTOR signaling pathway, mTOR inhibitors have been used as a treatment approach in tuberous sclerosis." (PMID 26248290, 2015). "Many of these, however, converge on the tuberous sclerosis genes TSC1 and TSC2, which produce the proteins hamartin and tuberin, respectively, and act as regulators of mTORC1." (PMID 21930185, 2012). "TSC2-deficient cells can proliferate in the lungs, kidneys, and other organs causing devastating progressive multisystem disorders such as lymphangioleiomyomatosis (LAM) and tuberous sclerosis complex (TSC)." (PMID 22719903, 2012). "Here we demonstrate, similar to previous reports using rapamycin, that RAD001 is highly effective in suppressing the growth of Tsc mouse kidney cystadenomas, with an average 99% reduction in tumor cell burden in this ENU-accelerated Tsc2+- model." (PMID 19527517, 2009). "Prenatal genetic testing for Tuberous Sclerosis Complex was performed in 9 cases (60%): 1 with a TSC1 mutation, 7 with TSC2 mutations, and 1 negative." (PMID 41438139, 2025). "Examples include large deletions encompassing TSC2 and PKD1, resulting in a combined phenotype of tuberous sclerosis complex and autosomal dominant polycystic kidney disease, as well as deletions involving COL4A5 and COL4A6, which cause Alport syndrome with diffuse leiomyomatosis." (PMID 41303235, 2025). "Alpha-[11C]methyl-L-tryptophan ([11C]AMT) PET shows increased tracer uptake interictally in epileptogenic tubers only of patients with tuberous sclerosis (TSC1 and TSC2) and in dysplastic cortex with an excellent agreement in seizure focus lateralization between ictal scalp EEG and [11C]AMT." (PMID 38393374, 2024). "Tissue remodeling as a consequence of deregulated TSC2 expression and/or function in the lung may include abnormal vasculature, loss of epithelial structure, smooth muscle cell accumulation, and formation of nonmalignant tumors as described in tuberous sclerosis and lymphangioleiomyomatosis (LAM)." (PMID 37874650, 2023). "As an example, Tsc1 and Tsc2 (Tuberous sclerosis complex) knockouts do not lead to the development of seizures in mice, unlike tuberous sclerosis cases in humans." (PMID 36428502, 2022). "Due to the low prevalence of tuberous sclerosis complex in Taiwan, we do not check the genetic screening for TSC1 or TSC2 mutation." (PMID 34445268, 2021). "TSC1 and TSC2 are a part of a complex in mice that, when not present such as in tuberous sclerosis, lead to uncontrolled mTORC1 activation." (PMID 32341806, 2020). "The “sporadic” form is observed in patients who do not have tuberous sclerosis (S-LAM), having only TSC2 gene mutation." (PMID 32471113, 2020). "Mutations in TSC2 are known to cause one syndromic form of ASD; however, our patient did not develop the classic symptoms of tuberous sclerosis until recently." (PMID 29458409, 2018). "For instance, although tuberous sclerosis patients were not considered in this study, the TSC2 gene was among the genes that accumulated more variation, most of which had a very low MAF." (PMID 28051113, 2017).